PYGL (glycogen phosphorylase L)
Description:
Allosteric enzyme that catalyzes the rate-limiting step in glycogen catabolism, the phosphorolytic cleavage of glycogen to produce glucose-1-phosphate, and plays a central role in maintaining cellular and organismal glucose homeostasis.
Synonyms: GSD6
Tractability: Small molecule: a structure with a bound ligand is known; a high-quality ligand is known; it has a high-quality binding pocket; it belongs to a druggable protein family. Antibody: its Gene Ontology location is reachable by antibodies, with high confidence; the Human Protein Atlas places it where antibodies can reach. PROTAC: ubiquitination databases record sites on it; its protein half-life has been measured; a small molecule that binds it is known.
Target class: Enzyme; Transferase
Chemical probes: PD070155
Gene: Protein-coding gene on chromosome 14 (50,857,891 to 50,944,734, reverse strand). Ensembl gene ENSG00000100504.
Subcellular location: Cytoplasm, cytosol
Subcellular location (Human Protein Atlas): Cytosol; Plasma membrane
Pathways (Reactome):
Immune System: Neutrophil degranulation
Metabolism: Glycogen breakdown (glycogenolysis)
Gene Ontology:
Molecular function: 1,4-alpha-oligoglucan phosphorylase activity; AMP binding; ATP binding; bile acid binding; D-glucose binding; glycogen phosphorylase activity; identical protein binding; protein binding; purine nucleobase binding; vitamin binding; pyridoxal phosphate binding
Biological process: glucose homeostasis; glycogen metabolic process; glycogen catabolic process; carbohydrate metabolic process
Cellular component: extracellular exosome; cytosol; extracellular region; ficolin-1-rich granule lumen; secretory granule lumen
Genetic constraint (gnomAD): Loss-of-function variants: 90 observed, 102.29 expected, observed/expected ratio (o/e) 0.88, 90% interval 0.74 to 1.05. The upper end of that interval is the gene's LOEUF score, 1.05, which puts it in group 4 of 6, group 1 being the genes least tolerant of losing a copy. Missense variants: 1,015 observed, 1,103.2 expected, observed/expected ratio (o/e) 0.92, 90% interval 0.87 to 0.97. Synonymous variants: 373 observed, 411.25 expected, observed/expected ratio (o/e) 0.91, 90% interval 0.83 to 0.99.
Gene-disease validity (ClinGen):
ClinGen rates the evidence that PYGL causes each of these diseases.
glycogen storage disease VI (autosomal recessive): Definitive. Liver phosphorylase deficiency, or glycogen storage disease type 6b (Hers' disease, GSD 6b) is a benign and rare form of glycogen storage disease.
Homologues: Orthologues: chimpanzee PYGL (99% identical), macaque PYGL (99% identical), dog PYGL (95% identical), guinea pig PYGL (95% identical), mouse Pygl (95% identical), rat Pygl (95% identical), rabbit PYGL (94% identical), pig PYGL (93% identical), tropical clawed frog pygl (86% identical), zebrafish pygl (83% identical), Drosophila melanogaster Glyp (72% identical), Caenorhabditis elegans pygl-1 (68% identical). Paralogues in human: PYGB (81% identical), PYGM (79% identical).
Diseases named in the same sentence as PYGL in open-access papers:
PYGL is named in the same sentence as 58 diseases in open-access papers, as found by Europe PMC text mining. Sharing a sentence is not in itself a finding about the gene and the disease. The quoted sentences say what the papers report.
breast carcinoma (11 papers, 2019 to 2026). "In the previous study, increased PYGL levels were analyzed to be linked with increased tumor size by utilizing mouse model of breast cancer, suggesting that PYGL participate in tumor progression." (PMID 34516362, 2021). "Moreover, elevated PYGL expression was strongly associated with reduced endocrine therapy sensitivity in breast cancer organoids and clinical tumor specimens." (PMID 41974649, 2026). "A previous study indicated that an increased PYGL expression level was associated with increased tumor size in breast cancer, suggesting that PYGL may participate in tumor progression." (PMID 35899200, 2022). "Collectively, these findings identify extracellular ATP-driven PYGL activation as a critical mechanism underlying endocrine resistance and suggest that targeting this pathway may represent a promising strategy to improve endocrine therapy efficacy in breast cancer patients." (PMID 41974649, 2026). "The regulation of PYGL in hypoxic conditions has not been characterized, although a recent study excludes hypoxia inducible factor (HIF) as a potential player in PYGL induction in glioblastoma and breast cancer cells." (PMID 37063425, 2023). "The hypoxia metabolism gene PYGL was discovered to be upregulated in many malignancies, including breast cancers and head and neck squamous cell carcinomas." (PMID 36699685, 2022). "The depletion of PYGL and decrease in glycogen accumulation decreased nucleotide synthesis and increased reactive oxygen species (ROS) levels, resulting in a decrease in breast cancer growth." (PMID 35899200, 2022). "PYGL is proposed as a hypoxia signal with prognostic significance in head and neck squamous cell carcinoma and breast cancer." (PMID 34512630, 2021). "In the two breast cancer cell lines, MDA-MB-231 and MCF-7, loss of the brain isoform PYGB inhibited hypoxic glycogen usage whereas the loss of both PYGL and PYGB in the normal-like MCF-10A cell line exhibited this effect." (PMID 31536495, 2019). "Regardless of the mechanism of hypoxic glycogen accumulation, we successfully inhibited glycogen utilization in breast cancer using shRNA knockdown of the glycogen phosphorylase isoforms PYGL and PYGB." (PMID 31536495, 2019). "Furthermore, PYGL depletion also decreases growth rate of cancer cells, induces cell cycle arrest and inhibits apoptosis in breast cancer, suggesting its oncogenic role." (PMID 34516362, 2021). "Meanwhile, the PYGL and G6PD levels in the primary tumors, including breast cancer, lung adenocarcinoma, and colon cancer, were positively correlated with poor patient survival." (PMID 38099490, 2023).
Glycogen storage disease type VI (8 papers, 2013 to 2026). "PYGL encodes liver glycogen phosphorylase, the rate-limiting enzyme in glycogenolysis, and 2 pathogenic variants result in glycogen storage disease type VI (GSDVI)." (PMID 41560719, 2026). "Glycogen storage disease type VI (GSD VI) is a rare disease in which liver glycogen metabolism is impaired by mutations in the glycogen phosphorylase L (PYGL)." (PMID 37264426, 2023). "Glycogen storage disease type VI (GSD VI) is an autosomal recessive disorder of glycogen metabolism due to mutations in the glycogen phosphorylase gene (PYGL), resulting in a deficiency of hepatic glycogen phosphorylase." (PMID 34440378, 2021). "PYGL inhibitors are already in development for treating type 2 diabetes and they are unlikely to be toxic to most cells because patients affected by Hers disease (an inherited glycogen storage disorder caused by deficiency of PYGL)." (PMID 32127786, 2020). "Mutations in the muscle isoform of mammalian glycogen phosphorylase (PYGM) cause glycogen storage disease type V (also known as McArdle's Disease), while mutations in the liver isoform (PYGL) cause glycogen storage disease type VI (also known as Hers' disease)." (PMID 24265594, 2013). "Glycogen storage disease type VI (GSD VI; OMIM #232700) is an inborn error of glycogen metabolism caused by mutation of the hepatic glycogen phosphorylase L (PYGL) gene located on chromosome 14q21-q22 with an autosomal recessive inheritance." (PMID 37264426, 2023). "Glycogen storage disease type VI (GSD VI, MIM 232700), Hers disease, is caused by mutations of the PYGL gene (MIM 613741) encoding hepatic phosphorylase on chromosome 14q21-q22." (PMID 33879691, 2021). "Glycogen storage disease type VI (GSD VI, OMIM #232700) is an inborn error of glycogen metabolism caused by biallelic mutations in the PYGL gene that result in a deficiency of hepatic glycogen phosphorylase (PYGL)." (PMID 34440378, 2021). "Glycogen storage disease VI (GSD VI; Hers disease; OMIM 232700) is a rare form of GSD caused by deficiency of liver phosphorylase due to compound heterozygous or homozygous mutations of PYGL." (PMID 32268899, 2020). "Deficiency in liver glycogen phosphorylase PYGL causes inability to break down liver glycogen and a glycogen storage disease type VI (also known as GSDVI or Hers disease)." (PMID 26882899, 2016).
glycogen storage diseases (7 papers, 2020 to 2025). "Genetic mutation of PYGL, a candidate for both CKD and MI, in human prevents effective glycogen breakdown in the liver leading to glycogen storage diseases." (PMID 37123453, 2023). "This study reported 12 Chinese patients with Glycogen storage disease and identified 18 gene variants of GAA, AGL, PHKA2 and PYGL (9 novel and 9 reported) by whole-exome sequencing." (PMID 36105079, 2022). "The screened GYS1, PYGL and PHKG1 genes play crucial roles in the glycogenolysis step of the glucagon signaling pathway, and their overexpression destabilizes glycogenolysis and predisposes one to glycogen storage disease, which can lead to cirrhosis and liver fibrosis." (PMID 36430769, 2022).
Hypoglycemia (6 papers, 2021 to 2025). A decreased concentration of glucose in the blood. "The transient neonatal hypoglycemia is accompanied by the secretion of glucagon, which turns on the glycogenolysis program by PYGL phosphorylation and GDE induction." (PMID 37826876, 2023). "Deficiency in PYGL and G6PT genes is known to manifest as hypoglycemia and excessive glycogen accumulation, causing GSD VI and GSD Ib, respectively, in humans." (PMID 35563842, 2022). "Collectively, these results indicate that the malfunctioning of PYGL due to the downregulation of gene expression and suppression of enzymatic activity in hepatocytes could be the primary cause of aberrant hepatic glycogen accumulation and hypoglycemia in Ndrg3 LKO mice." (PMID 35563842, 2022). "All 7 unrelated GSD VI patients (harboring the founder PYGL variant c.1768 + 1 G > A from different regions in Saudi Arabia) manifested a mild phenotype characterized by hepatomegaly without hypoglycemia or significant complications/comorbidities." (PMID 40743267, 2025). "GSD III (AGL, MIM# 232400), VI (PYGL, MIM# 232700) and IXα (PHKA2, MIM# 306000) belong to hepatic GSD with basic features of hepatomegaly and hypoglycemia." (PMID 36105079, 2022). "These mouse models do not show hypoglycemia, likely because they exhibit intact hepatic G6PC activity and functional glycogen degradation through PYGL." (PMID 37995884, 2024).
pancreatic cancer (6 papers, 2021 to 2025). "Bioinformatics analyses of pancreatic cancer public datasets showed that glycogen phosphorylase L (PYGL) expression is elevated in quasimesenchymal PDAC (QM-PDAC) and positively associated with EMT." (PMID 37063425, 2023). "Previous researches also reported that PYGL could promote metastasis in pancreatic cancer, while disruption of PYGL induces necroptosis." (PMID 37420300, 2023). "TRIM9 was found to be a protective factor for pancreatic cancer in both the bbj_a_140 and ebi-a-GCST90018673 datasets, and it exhibited colocalization with genes such as TMX1 and PYGL." (PMID 41050689, 2025). "Seven GRGs: CDK1, DSC2, MET, PYGL, CHST12, ERO1A, and SLC35A3 were selected to construct the prognostic model related to the overall survival rate of patients with pancreatic cancer." (PMID 33912561, 2021). "Expression analysis further revealed that CDK1, DSC2, ERO1A, MET, PYGL, and SLC35A3 were highly expressed in pancreatic cancer while CHST12 was highly expressed in normal pancreatic tissues." (PMID 33912561, 2021). "CDK1, DSC2, ERO1A, MET, PYGL, and SLC35A3 were highly expressed while CHST12 was decreased in pancreatic cancer." (PMID 33912561, 2021).
diabetes (5 papers, 2018 to 2022). "We found that KIF22 was significantly associated with age, history of diabetes, alcohol history and neoplasm_histologic grade, while PYGL was markedly correlated with neoplasm_histologic grade (p < 0.05)." (PMID 34257566, 2021). "Of note, small molecule inhibitors of PYGL are currently under investigation for the treatment of diabetes." (PMID 30820706, 2019). "These previous studies reported that the expression of TRIM4 and PYGL in colon transverse tissue was associated with colorectal cancer risk, while PTPN2 expression in colon transverse tissue modified the association of diabetes with colorectal cancer risk." (PMID 33142733, 2020). "The hyperglycemia observed in diabetes results frompancreatic dysfunction and insulin resistance, and is associated with unbalancedglycogenolysis and gluconeogenesis.Previous studies observed significant correlation between insulin resistance andPCK1, G6PC, and PYGL levels." (PMID 35976267, 2022). "We identified key genes (GYS1, PYGL, and PSAT1) from both pathways that have previously been demonstrated to play a role in glucose tolerance/ insulin sensitivity in models of obesity and diabetes and epidemiological studies." (PMID 30483256, 2018).
glioma (5 papers, 2021 to 2025). A benign or malignant brain and spinal cord tumor that arises from glial cells (astrocytes, oligodendrocytes, ependymal cells). "The differentially expressed and mutational profile of glioma was constructed, and four targetable antigens (ANXA5, FKBP10, MSN, and PYGL) were further confirmed." (PMID 34512630, 2021). "Four glioma antigens, namely ANXA5, FKBP10, MSN, and PYGL, associated with superior prognoses and infiltration of APCs were selected." (PMID 34512630, 2021). "At this point, we presumed that PYGL activates the central node of mTORC1 and alternates the glycogen metabolism by reprogrammed the glycolytic pathway, and then allows glioma cells to survive and adapt to restricted nutrition conditions." (PMID 34177761, 2021). "This study was designed to investigate the predictive value of high PYGL expression in patients with gliomas through bioinformatics analysis of the gene transcriptome and the single-cell sequencing data." (PMID 34177761, 2021). "OS analysis and Cox regression analyses showed high expression of PYGL was an independent factor for poor prognosis of gliomas (p < 0.05)." (PMID 34177761, 2021). "In this study, we found that the expression level of PYGL was positively correlated with the malignant grade of gliomas." (PMID 34177761, 2021). "Differential analysis was used to find the distribution of expression of PYGL in different groups of glioma patients." (PMID 34177761, 2021). "In summary, this study has shown that the high expression of PYGL has independent predictive value in the poor prognosis of patients with gliomas." (PMID 34177761, 2021). "Overall, these results indicated that the expression of PYGL had independent predictive value in the prognosis of glioma patients and high PYGL expression predicted poor prognosis in human gliomas." (PMID 34177761, 2021). "Univariate analysis and multivariate analysis of the correlation between PYGL expression with OS among glioma patients." (PMID 34177761, 2021). "The mRNA expressions of PYGL in gliomas among groups with different clinical characteristics were compared using the Kruskal–Wallis test or Wilcoxon test." (PMID 34177761, 2021). "In the present study, we provide evidence that high PYGL expression plays an independent role in predicting the poor prognosis of glioma patients." (PMID 34177761, 2021). "The C index was 0.81, indicating that high PYGL expression had medium accuracy in predicting poor prognosis in human gliomas." (PMID 34177761, 2021). "The results showed that PYGL expression was significantly higher in the WHO IV grade glioma tissues than that in WHO II grade group (P = 2.85e-56) and WHO III grade group (P = 1.16e-22)." (PMID 34177761, 2021). "We also found that the expression level of PYGL was negatively correlated with the survival time of patients with gliomas." (PMID 34177761, 2021). "Four antigens ANXA5, FKBP10, MSN, and PYGL were promising to develop mRNA vaccine against glioma." (PMID 34512630, 2021). "Therefore, the high expression of PYGL has independent predictive value in the poor prognosis of glioma patients." (PMID 34177761, 2021). "This indicated that the high expression level of PYGL in high-grade gliomas was not caused by the age of the patient." (PMID 34177761, 2021). "Our enrichment plots data suggest that PYGL may induce glioma proliferation through up-regulation of mTORC1 signaling, PI3K/AKT/mTOR signaling, KRAS signaling up, and angiogenesis pathway." (PMID 34177761, 2021). "The AUC values were 0.838 (1-year ROC), 0.864 (3-year ROC), and 0.833 (5-year ROC), which showed that the expression of PYGL could reliably predict the 1-, 3- and 5-year survival rate of patients with gliomas." (PMID 34177761, 2021). "However, there have been no previous studies to explore the relationship between the expression of PYGL and the prognosis of patients with gliomas." (PMID 34177761, 2021).
glioma (continued). "Therefore, we innovatively put forward hypotheses that gliomas are rich in PYGL-mediated G6P which may participate in tumor growth, and glycogen metabolism is an important event in the tumor immune escape process." (PMID 34177761, 2021). "Thus, we focus on PYGL only to explain the malignancy of glioma in this study." (PMID 34177761, 2021). "In WHO grade IV glioma groups, by adjusting to a lower threshold and re-conducting survival analysis, the results showed that the effect of survival time was significant, which proved that the high expression of PYGL was related to the worse prognosis of patients with WHO grade IV gliomas." (PMID 34177761, 2021). "Four glioma antigens were identified, including FKBP prolyl isomerase 10 (FKBP10), glycogen phosphorylase L (PYGL), annexin A5 (ANXA5), and moesin (MSN), which were correlated with elevated APC infiltration and better prognoses." (PMID 40948290, 2025). "Subgroup analysis showed that the high expression of PYGL had a significant effect on the OS of WHO grade II/III and different age groups of gliomas." (PMID 34177761, 2021). "The amplified expressions of ANXA5, FKBP10, MSN, and PYGL were correlated with favorable prognosis OS and DFS of glioma, which exert pivotal roles in glioma development and progression." (PMID 34512630, 2021). "Results showed that high PYGL expression was an independent predictor of poor prognosis in PRAD patients, consistent with a pervious study that reported similar findings in glioma patients." (PMID 35111740, 2021). "There was no explicit discussion of the difference in PYGL expression between glioma and normal brain." (PMID 34177761, 2021). "TAMs express PYGL and GYS1 highly, which may be one reason for glioma proliferation and immune escape." (PMID 34177761, 2021).
brain cancer (4 papers, 2021 to 2022). A primary or metastatic malignant neoplasm affecting the brain. "Despite the high expression of PYGL is related to the malignant proliferation of brain cancer cells, the underlying mechanism of it is still unclear." (PMID 34177761, 2021). "Several studies found that PYGL expression was upregulated in several cancers, including seminoma, brain cancer, and papillary renal cell carcinoma." (PMID 35899200, 2022). "A meta-analysis of more than 2,000 cases showed that PYGL was upregulated in several cases, including clear cell renal cell carcinoma, seminoma, and brain cancer, especially in the hypoxic tumor microenvironment." (PMID 34512630, 2021).
colon cancer (4 papers, 2022 to 2025). "RNA-seq data from The Cancer Genome Atlas (TCGA) and the Genotype-Tissue Expression project (GTEx) revealed that both PYGL and HLA-B were expressed at higher levels in normal tissues adjacent to colon cancer than in tumor tissues or normal tissues derived from subjects without cancer." (PMID 35204406, 2022). "Notably, TMEM220-AS1, TMEM238L, SOX6, SMAD7, TCF7L2, and PYGL were significantly downregulated in colon cancer, whereas LINC02257, PCAT1, CASC8, and POU5F1B were significantly upregulated in colon cancer." (PMID 41144378, 2025).